POLR3F (RNA polymerase III subunit F)
Description:
DNA-dependent RNA polymerase catalyzes the transcription of DNA into RNA using the four ribonucleoside triphosphates as substrates. Specific peripheric component of RNA polymerase III (Pol III) which synthesizes small non-coding RNAs including 5S rRNA, snRNAs, tRNAs and miRNAs from at least 500 distinct genomic loci. Part of POLR3C/RPC3-POLR3F/RPC6-POLR3G/RPC7 heterotrimer that coordinates the dynamics of Pol III stalk and clamp modules during the transition from apo to elongation state. Pol III plays a key role in sensing and limiting infection by intracellular bacteria and DNA viruses, including varicella zoster virus. Acts as a nuclear and cytosolic DNA sensor detecting AT-rich DNA, involved in innate immune response. Can sense non-self dsDNA that serves as template for transcription into dsRNA. The non-self RNA polymerase III transcripts, such as Epstein-Barr virus-encoded RNAs (EBERs) induce type I interferon and NF-kappa-B through the RIG-I pathway. Preferentially binds double-stranded DNA (dsDNA).
Synonyms: RPC39; RPC6; C34; IMD101
Tractability: Small molecule: a structure with a bound ligand is known. PROTAC: UniProt records ubiquitination sites on it; ubiquitination databases record sites on it; its protein half-life has been measured.
Gene: Protein-coding gene on chromosome 20 (18,466,878 to 18,484,648, forward strand). Ensembl gene ENSG00000132664.
Subcellular location: Nucleus
Subcellular location (Human Protein Atlas): Nucleoplasm
Pathways (Reactome):
Gene expression (Transcription): RNA Polymerase III Abortive And Retractive Initiation; RNA Polymerase III Chain Elongation; RNA Polymerase III Transcription Initiation From Type 1 Promoter; RNA Polymerase III Transcription Initiation From Type 2 Promoter; RNA Polymerase III Transcription Initiation From Type 3 Promoter; RNA Polymerase III Transcription Termination
Immune System: Cytosolic sensors of pathogen-associated DNA
Gene Ontology:
Molecular function: 4 iron, 4 sulfur cluster binding; double-stranded DNA binding; protein binding; DNA-directed RNA polymerase activity
Biological process: positive regulation of innate immune response; positive regulation of interferon-beta production; termination of RNA polymerase III transcription; transcription by RNA polymerase III; transcription initiation at RNA polymerase III promoter; regulation of transcription by RNA polymerase III
Cellular component: nucleus; RNA polymerase III complex; cytosol; nucleoplasm; cytoplasm
Genetic constraint (gnomAD): Loss-of-function variants: 8 observed, 14.26 expected, observed/expected ratio (o/e) 0.56, 90% interval 0.33 to 1.01. The upper end of that interval is the gene's LOEUF score, 1.01, which puts it in group 4 of 6, group 1 being the genes least tolerant of losing a copy. Missense variants: 86 observed, 122.26 expected, observed/expected ratio (o/e) 0.7, 90% interval 0.59 to 0.84. Synonymous variants: 30 observed, 44.07 expected, observed/expected ratio (o/e) 0.68, 90% interval 0.51 to 0.92.
Homologues: Orthologues: chimpanzee POLR3F (100% identical), dog POLR3F (99% identical), rabbit POLR3F (99% identical), pig POLR3F (99% identical), rat Polr3f (99% identical), mouse Polr3f (99% identical), guinea pig POLR3F (98% identical), macaque POLR3F (95% identical), zebrafish polr3f (89% identical), tropical clawed frog polr3f (87% identical), Drosophila melanogaster Polr3F (48% identical), Caenorhabditis elegans W09C3.4 (33% identical).
Diseases named in the same sentence as POLR3F in open-access papers:
POLR3F is named in the same sentence as 10 diseases in open-access papers, as found by Europe PMC text mining. Sharing a sentence is not in itself a finding about the gene and the disease. The quoted sentences say what the papers report.
chickenpox (1 paper, 2022). A contagious childhood disorder caused by the varicella zoster virus. "Heterozygous mutations in genes encoding four Pol III subunits, POLR3A/RPC1, POLR3C/RPC3, POLR3E/RPC5, POLR3F/RPC6, compromise this immune response to Varicella Zoster Virus (chickenpox)." (PMID 35813003, 2022).
encephalitis (1 paper, 2021). An acute inflammatory process affecting the brain parenchyma. "Mutations in the POLR3A, POLR3C, POLR3E and POLR3F subunits are associated with susceptibility to varicella zoster virus-induced encephalitis and pneumonitis." (PMID 34395528, 2021).
meningioma (1 paper, 2020). A generally slow growing tumor attached to the dura mater. "Among the 2N patients, we detected six genes (POLR3F, SEC23B, ZNF133, C16orf45, RRN3, and NTAN1) which were overexpressed after irradiation and were duplicated in the genome of ALL patients with the second independent cancer being either meningioma or thyroid carcinoma." (PMID 32577795, 2020).
POLR3F also shares sentences with these, for which no sentence is quoted: cancer (2 papers); HIV-1 infection (2); infection (2); Autoimmunity (1); pneumonitis (1); thyroid carcinoma (1); tumor (1).